TLR3 (toll like receptor 3)
Diseases named in the same sentence as TLR3 in open-access papers (continued):
Sharing a sentence is not in itself a finding about the gene and the disease.
infection (continued). "In addition to the induced Ifn-λ expression, we demonstrate that also the chemokine Rantes, known to induce the recruitment of immune effector cells to the site of infection, is expressed in a Tlr3/Trif-dependent manner in adult mice." (PMID 22570612, 2012). "In terms of source of intracellular nucleic acids, consistent with the binding activity of S100B in vitro, we found that fungal RNA not only complexes with S100B in infection but also activates epithelial cells in a TLR3–dependent manner, as indicated by IRF3 phosphorylation." (PMID 21423669, 2011). "In addition, TLR3 mice showed higher levels of some pro-inflammatory cytokines four days after infection, consistent with compensatory activation of another host pattern recognition receptors." (PMID 21637773, 2011). "In addition, TLR3 appears to play a protective role against infections with West Nile virus (WNV), Coxsackievirus B4, and mouse cytomegalovirus." (PMID 22189096, 2011). "Furthermore, our data suggests that the amount of IFN induced by HCV depends on the expression levels of TLR3 itself at the time of infection." (PMID 21695051, 2011). "Interestingly, Tlr3 showed up regulation at all the time points of infection but there was an increase in level of expression at 1 and 4 DPI." (PMID 21371334, 2011). "Importantly, we observed that cIBDV infection upregulated the expression of TLR3 whereas vIBDV infection downregulated its expression." (PMID 21749706, 2011). "TLR3 deficient mice challenged with EMCV had decreased levels of TNFα, IL-6 and IL-1β mRNA in cardiac tissue and a corresponding reduction in inflammatory infiltrate at 3 days post infection." (PMID 21994762, 2011). "IFNs-α, -β, -λ2 and -λ3 each showed brisk responses following RV1B infection of TLR3−/− mice." (PMID 21637773, 2011). "However, TLR3 stimulation plays a protective role in infection with GDVII, a neurovirulent TMEV strain." (PMID 22189096, 2011). "Interestingly, the secretion of IL-12 following infection with the highly stimulatory vhs-deletion virus was enhanced when TLR3 was present." (PMID 20174621, 2010). "Furthermore, RIG-I and MDA5 were virus inducible genes, induced early via a TLR3/TRIF pathway, indicating that TLR3 acts as an initial endosomal sensor and must induce the RNA helicases for maximal anti-viral defense during the course of infection." (PMID 21079690, 2010). "In contrast, infection by higher MOI of DENV activates stronger TLR-3 and -4 expressions." (PMID 21200427, 2010). "Interestingly, upon comparing the secretion of IL-12 from the three different knock-out conditions during vhs- infection it was apparent that the presence of TLR3 significantly augments the response to the highly stimulatory vhs- virus." (PMID 20174621, 2010). "Moreover, Tbk1−/− MEF show marked defects in type I IFNs, Cxcl10, and RANTES gene expression after infection with either Sendai or Newcastle disease viruses or after engagement of the TLR3 and TLR4 by double-stranded RNA and LPS, respectively." (PMID 20090833, 2010). "Here, we demonstrate that the early immune response to CB4 is solely dependent on TLR3 signaling as infection of TLR3 deficient but not MyD88 deficient mice had fatal consequences." (PMID 19122812, 2009). "Majority of cells harbour one or two perinuclear TLR3 aggregates 24 h after infection." (PMID 19247444, 2009). "In our model, sequestration of TLR3 could be a way for the virus to prevent a TLR3-mediated pro-apoptotic response to infection, as neuronal integrity is required for RABV propagation though the CNS." (PMID 19247444, 2009). "Based on these reports, we are currently investigating the interaction between RLHs and CB4 and speculate that this virus may be able to abrogate signaling from RLHs potentially explaining the critical role of TLR3 over the course of infection." (PMID 19122812, 2009).
infection (continued). "The presence of viral RNA in NBs may reflect an interaction of TLR3 with viral components at an early stage of infection, when the virus enters the cell through the TLR3 decorated endosomal compartment." (PMID 19247444, 2009). "Interestingly, we observed a significantly reduced level of IL-6 and IFN-γ following infection of MyD88KO mice compared to WT NOD indicating that these cytokines are produced following ligation of TLRs other than TLR3." (PMID 19122812, 2009). "However, several reports have demonstrated that TLR3 signaling is either dispensable or even harmful following infection with certain viruses." (PMID 19122812, 2009). "For example, homozygous deletion of TLR3 (Toll-like receptor 3) (4q35.1), which functions in the innate immune response and is also highly expressed in pancreas, suggests a possible role of infection in pancreatic carcinogenesis." (PMID 18535672, 2008). "Additionally, the Affymetrix microarray technology provides evidence that infection of the TLR3-expressing human post-mitotic neuron derivative cell line NT2-N with HSV1 triggers IL6 and IRF1 mRNA production." (PMID 19088911, 2008). "However, the TLR3 rs3775291 C/T polymorphism was linked to higher TLR3 expression levels and the absence of infection by the HCV1a viral genotype, which is associated with severe prognosis." (PMID 40831704, 2025). "Similarly, IRF-3 mRNA levels experienced a significant reduction post-TLR3 silencing at all time points following H9N2 AIV infection (p < 0.005), aligning with the trends observed for NF-κB and highlighting the interconnected regulatory mechanisms governing IRF-3 expression." (PMID 38731436, 2024). "Thus, we correlated the RV-A1b mRNA expression and TLR3 mRNA upon RV-A1b infection in A549." (PMID 38140569, 2023). "TLR3 in the immune response of golden pompano may act as a pattern recognition receptor (PRR) transmitting signals to downstream pathways against the pathogen infection." (PMID 36670828, 2023). "Therefore, more studies are necessary to fully elucidate the role of TLR3 rs3775291 in infections." (PMID 37510216, 2023). "During infection with WNV, TLR3-deficient mice were found to be more resistant to the lethal WNV infection; the authors hypothesized that this was due to reversible breakdown of the BBB evoked by a TLR3-dependent inflammatory response." (PMID 36834929, 2023). "TLR3 is critical for the induction of the antiviral state and the prevention of virus replication, but it can also promote an overactive and dysregulated immune response to infection, which is damaging to the host and helps to progress the severe form of the disease." (PMID 37510216, 2023). "Additionally, production of type III interferons was shown to be dependent on TLR3 signaling as mice lacking TLR3 were more susceptible to infection and had significantly reduced levels of IFN-λ." (PMID 37325809, 2023). "For instance, endosomal TLR3 and TLR7, and cytosolic retinoic acid-inducible gene I (RIG-I) and melanoma differentiation-associated protein 5 (MDA5) have been shown to sense the DENV RNA early in the infection, thereby leading to the production of type I interferons." (PMID 36240261, 2022). "However, mice lacking TLR3 were more susceptible, resulting in an 8-fold increase in parasite shedding and an overall pattern of infection that was reminiscent of Ifnlr1-/- mice (AUC, Standard t-test * p <0.05)." (PMID 35584177, 2022). "Furthermore, we found that TLR3 is required for the downmodulation of inflammatory responses in L. donovani-infected macrophages and parasite intracellular growth, connecting typical anti-viral innate responses to the promotion of parasite infection." (PMID 35154115, 2022).
infection (continued). "Interestingly, TLR3-mediated IFN production after infection with Herpes simplex virus 1 (HSV-1) is cell type-dependent, with TLR3 limiting HSV-1 replication in mouse fibroblasts and CNS-resident cells (neurons, astrocytes), whereas no such protective mechanism is produced in mouse macrophages." (PMID 36091073, 2022). "Furthermore, the induction of IL10 and of SOD1 gene expression was also dependent on TLR3, showing that the anti-viral-type responses conveyed via PKR and TLR3 are mobilized by L. donovani to downmodulate the inflammatory response of macrophages, likely influencing infection." (PMID 35154115, 2022). "In addition, the negative regulation of miR-148a-5p by TLR3 may be one of the reasons for the low expression of miR-148a-5p after DTMUV infection, but more experiments are required to explore the mechanism by how TLR3 negatively regulates miR-148a-5p." (PMID 31947624, 2020). "Besides TLR3, other TLRs target the MyD88 pathway to resist pathogen infection." (PMID 31947624, 2020). "We show that TLR3 deficiency leads to more rapid ascension into the UGT of infected mice, and we attribute the more rapid ascension to dysregulation in the C. muridarum-induced syntheses of critical immune modulators and the increased infection-induced disruption of cell-cell junctions." (PMID 30625140, 2019). "By day 7 post-infection, the CD4+ T-cell populations in the wild-type and TLR3-deficient mice were 64.8% and 69%, respectively, which represented an increased frequency of CD4+ T-cells in the genital tract of wild-type and TLR3-/- mice was 38.2% and 46.8% over the mock controls." (PMID 29624589, 2018). "Collectively, these results suggest that TLR3 may be involved in modulating the recruitment of CD4 T-cells required to clear C. muridarum from the genital tracts of C57BL/6N mice during middle stages of infection." (PMID 29624589, 2018). "In addition, the kinetics of CD4+ T-cells in the genital tract of TLR3-/- mice during the early and middle stages of infection is similar to what is observed during C. muridarum infections in BALB/c and C57BL/6 mice showing that Th1 T-cells remain high after 3 weeks post-infection." (PMID 29624589, 2018). "In addition, our previous in vitro studies showed that Chlamydia replication was more robust in the TLR3-/- OE cells when compared to wild-type, and that pretreating the TLR3-/- OE cells with IFN-β prior to infection significantly reduced chlamydial replication in these cells." (PMID 29624589, 2018). "The importance of TLR3 in context of cardiovirus infection may depend on the model of infection." (PMID 30369921, 2018). "Also, a study that evaluated the role of TLR3 in controlling a strain of EMCV with tropism for β cells of the pancreas found that TLR3 protected mice from a fatal infection and that TLR3-deficent mice produced less IFN-β early in infection (15 and 18 h post-infection)." (PMID 30369921, 2018). "However, this deficiency was transient and mice lacking TLR3 produced levels of IFN-β equivalent to wild-type animals at 24 h post-infection." (PMID 30369921, 2018). "Interestingly, at early time points, infection with LgyLRV1+ parasites significantly increased A20 expression compared to both LgyLRV1- infection or poly(I:C) treatment, suggesting an additive effect between Leishmania infection and TLR3 stimulation." (PMID 29487860, 2018). "A more recent study showed that the three nucleic acid sensing TLRs, TLR3, 7 and 9, are crucial for a protective response against L. major infection, as mice which lacked all of these functional TLRs (i.e. TLR3/TLR7/TLR9−/− or UNC93B1−/− mice) were highly susceptible to infection." (PMID 27716391, 2016). "Infection at delivery, but not earlier in pregnancy, was associated with significantly higher TLR3-mediated IL-6 and IL-10 responses in the first 3 months of life, and with significantly higher TLR3-/TLR7/8-/TLR9-mediated TNF-α and TLR9-mediated IL-10 responses at 6 or 12 months of age." (PMID 26580401, 2015).
infection (continued). "In this context, loss of function mutation in the filaggrin gene breaks the epithelial barrier and causes further cell damage, which could be brought about by repeated scratching behavior or infection, leading to deterioration of AD through activation of such a TLR3-dependent mechanism." (PMID 25171086, 2014). "However, the route of infection and type of virus may very well determine TLR3’s role during infection." (PMID 23435233, 2013). "Therefore, the high sensitivity demonstrated by the Myd88−/− Trif−/− double deficient mice to infection is in accordance with a role for TLR4 and/or TLR3 in the response against T. cruzi, as these members of the TLR family are the only known to use TRIF as a transducer molecule." (PMID 22496959, 2012). "In addition, we found abrogation – or almost complete suppression – of infection by pseudoviruses containing the BaL or BR envelope glycoproteins in MDMs stimulated through TLR3 or TLR4, with only partial reduction observed in cells stimulated through TLR2, TLR7 or TLR9." (PMID 23028330, 2012). "Likewise, TLR3 was shown to play a pathologic role in infections with Punta Toro Virus (PTV)." (PMID 21994762, 2011). "The controversial reports on the role of TLR3 in the antiviral defense may be due to the difference in the type of viruses, the type of cells that are infected, the viral load, its model of infection (endoplasmic versus cytoplasmic), and stage of infection." (PMID 20936107, 2010). "Thus, TLR3 is not expressed at the surface, at least at detectable levels, and infection does not cause TLR3 to relocate towards the cell surface." (PMID 19247444, 2009). "By contrast, infection with GNU-2353 and GNU-2377 induced a significant decrease in TLR expression, although TLR3 was slightly promoted in cells infected with either virus at 48 hpi." (PMID 40302751, 2025). "Among these proteins, in particular, TLR3 activated MSCs secreted TNFSF10, CXCL10, ISG15 and C2 (green highlight, 7C) were found upstream of several affected immune response and infection pathways in all 3 cell types." (PMID 40861855, 2025). "During the later stages of infection, TRIM38 negatively regulates the TLR3/4 signaling, consequently suppressing the production of proinflammatory cytokines including TNF-α, IL-1β, and IL-6." (PMID 40006954, 2025). "Surprisingly, only one study so far has validated TLR3 sensing of SARS-CoV-2, showing that TLR3 activation upon infection of multicellular lung spheroids leads to type I IFN and cytokine production via the IRF3 signaling pathway." (PMID 39963132, 2025). "While lung expression of TLR3, DDX58 and NLRP3 remained unchanged in WT mice following infection, it was significantly higher in TLR7 KO mice." (PMID 40442368, 2025). "After infection has been established, intracellular viral RNA can be recognized by the endosomal TLR7 and 8, or TLR3, which sense ssRNA or dsRNA, respectively." (PMID 39963132, 2025). "While DENV-2 infection-induced up-regulation of TLR2 and TLR7 mRNA during the early stages of infection (1.5 and 3 h.p.i), the mRNA expression of TLR2, TLR3, TLR4, TLR7, and TLR8 reaches its maximum peak of expression at 24 h.p.i." (PMID 40934228, 2025). "In mature chicken BmDCs, 6 h of infection with NDV LaSota was shown to increase the expression of MDA5, LGP2, TLR3, TLR7, and type I IFN IFN-α and IFN-β." (PMID 39967657, 2025). "In leukocytes, PLAUR positively correlated with RIG-I and MDA5 which changed to TLR3, TLR6, and TLR8 with infection; PLAU, on the other hand, lost its correlation with TLR4 and TLR5 with COVID19." (PMID 40825056, 2025). "In summary, EV-A71 infection activates a multifaceted immune response in the intestinal mucosa, dominated by type III IFN production through the TLR3/IRF1 axis." (PMID 41472211, 2025).
infection (continued). "Apoptotic markers (caspase-3, Bax, Bcl-2) were analyzed by immunofluorescence and immune genes expression kinetics (TLR3/7, RIGI, MDA5, IL-1β, IL-6, TNFα, IL-10, IFNβ and β-catenin) were measured at defined time points post-infection by RT-qPCR." (PMID 41157617, 2025). "In contrast, TLR1, TLR3 and TLR5, expression was significantly downregulated, whereas TLR6 remained unchanged throughout the infection period." (PMID 41305370, 2025). "We observed that M-CSF-differentiated BMDMs minimally expressed CD103 at baseline but showed robust upregulation after exposure to endosomal TLR ligands (TLR3, TLR7, TLR9) or infection with LCMV." (PMID 40630637, 2025). "In DENV-infected K562 cells, delayed expression of TLR3 and IFNAR1 was observed, accompanied by a progressive increase in IFN-β secretion, which reached its peak concentration three days post-infection." (PMID 41303574, 2025). "These cells recognize viral RNA through recognition receptors such as TLR3, TLR7, and TLR8 and respond to infection by secreting inflammatory cytokines." (PMID 38268832, 2024). "Six TLRs recognize the presence of SARS-CoV-2 (TLR2, TLR3, TLR4, TLR7, TLR8, and TLR9), of which TLR2, TLR4, and TLR9 favor the pathogenicity of the virus, while TLR3, TLR7, and TLR8 favor control of the infection and resolution of the disease." (PMID 39062904, 2024). "TLR3 is capable of triggering IFN and cytokine production during infection with VSV (vesicular stomatitis virus), EMCV (encephalomyocarditis virus), and WNV (West Nile virus), indicating that TLR3 acts as a direct viral sensor." (PMID 38343534, 2024). "The observed inhibition of PKR and Mx1 mRNA expression after H9N2 AIV infection underscores OMT’s potential to interfere with host–virus interactions at the molecular level, possibly through modulation of TLR3 signaling." (PMID 38731436, 2024). "Our studies revealed an increase in TLR3 expression and phosphorylation of NF-κB following RRV and Ro1845VP4-G446R infection, as well as an increase in the cytokines CXCL9 and CXCL10." (PMID 38860860, 2024). "Leukocytes expressing TLR2, TLR3, TLR4, TLR6, and TLR7 also interact with RSV, promoting immune responses post-infection." (PMID 38892370, 2024). "One study reported that TLR-3 expression levels significantly increased at 4 hpi and 16 hpi with HPAI H7N1 infections, whereas the level of increase in HPAI H5N2s were more gradual." (PMID 39281683, 2024). "Astrocytes can activate innate antiviral pathways upon infection with HSV-1–such as IL-6, TNF-α, and type I IFN production via the TLR3-dependent pathway in HSV-2 infection." (PMID 39339840, 2024). "In this study, we cultured bone-derived chicken dendritic cells (ck-BM-DC) and examined gene expression levels of IFN-α, TLR-3, TLR-7, MHC-I, IL-1β, IL-6, Mx, Casp-3, and Casp-8 pre/post infection with AIV." (PMID 39281683, 2024). "When monocytes were infected with ncp BVDV, the mRNA levels of TLR3, type I IFN and IL-12 were significantly increased at 1 h post infection, whereas the TLR7 mRNA was significantly upregulated in monocytes infected with both biotypes at 24 h post infection." (PMID 37900320, 2023). "To explore the existence of TLR-TLR crosstalk, we therefore treated wildtype and Tlr4−/− iBMDMs with inhibitors of TLR2 (CU CPT22), TLR3 (TLR3/dsRNA complex inhibitor), and TLR9 prior to infection with C. neoformans." (PMID 37580395, 2023). "The expressions of TLR3 and TLR4 were increased by infection with different ZIKV strains, and the expression of TLR5 appeared unaffected 2 days after infection." (PMID 36834929, 2023). "In contrast, the BPH-1 cells are strong inducers of IFN-I at a high multiplicity of infection and respond to IFN-I after P/V/F mutant infection, with induction of three key ISGs (OAS2, IFIT1 and TLR3), indicating the establishment of an anti-viral state." (PMID 35631014, 2022).